IL24 (interleukin 24)
Diseases named in the same sentence as IL24 in open-access papers (continued):
Sharing a sentence is not in itself a finding about the gene and the disease.
COVID-19 (7 papers, 2022 to 2025). A disease caused by infection with severe acute respiratory syndrome coronavirus 2. "Elevated IL-24 serum levels were associated with milder COVID-19 courses, suggesting a protective role in modulating immune responses and promoting antiviral apoptosis." (PMID 40943325, 2025). "Targeting IL-24 pathways therapeutically could help enhance viral clearance and mitigate severe COVID-19 outcomes, particularly among patients with low IL-24 levels or those at elevated risk for ARDS." (PMID 40943325, 2025). "Additionally, reduced liver function could impact IL-24 synthesis or regulation, compounding its deficiency in severe COVID-19 cases." (PMID 40943325, 2025). "Through the analysis of the propensity score-matched biomarker screening cohort, we identified Flt3L, TRAIL, CXCL5, IL-12B, MCP-3, IL-24, and IL-8 as candidate biomarkers for severe progression of COVID-19 in elderly patients." (PMID 40426989, 2025). "This is consistent with previous data describing IL-24 as one of the least abundantly expressed proteins in hospitalized COVID-19 patients." (PMID 40943325, 2025). "IL-24 serum concentrations were assessed in 41 COVID-19 patients (88 samples) across critical, severe, moderate, and mild disease courses." (PMID 40943325, 2025). "Interleukin-24 (IL-24) is a cytokine known for its role in immune regulation and apoptosis, with potential implications in viral infections like COVID-19." (PMID 40943325, 2025). "By contrast, we saw a decrease in cytokines related to the remodeling of the extracellular matrix in COVID-19 (e.g., decreased expression of IL24 and insulin-like growth factor)." (PMID 35743918, 2022). "Further research is essential to elucidate IL-24′s specific antiviral effects against SARS-CoV-2 and its interactions with key immune pathways in COVID-19 pathophysiology." (PMID 40943325, 2025). "Patients with severe COVID-19 have elevated plasma levels of the IL10 family of cytokines, IL19, and IL24, which decrease during recovery." (PMID 38543303, 2024). "The majority of COVID-19 patients in our study, with critical or severe disease (oxygenation impairment) showed no IL-24 concentrations above the LLOQ during their hospital stay, as determined from serial blood samples collected at time points H1–H5." (PMID 40943325, 2025).
oral cancer (7 papers, 2015 to 2022). "Further, miR-205 in the KB oral cancer cells induced tumour suppressor gene IL-24 mRNA and protein by targeting its promoter." (PMID 33109127, 2020). "This work highlights the potential of combination of IL-24 gene and autophagy inhibitor for enhanced efficacy against aggressive oral cancer." (PMID 26361755, 2015). "There also was a study that showed that the transfection of miR-205 into human oral carcinoma (KB) cells strongly induced the IL24 mRNA, which targeted the IL24 promoter directly to induce gene expression and had significant therapeutic potential to turn on silenced tumor suppressor genes." (PMID 33014054, 2020). "In addition, miRNA-205, which is silenced in human prostate cell lines, has been shown to directly target the IL-24 promoter to induce gene expression in human PCa and oral cancer cells." (PMID 30669553, 2019). "A report showed that miR‐205 up‐regulates IL‐24 in KB oral cancer." (PMID 28781949, 2017). "Querying the TCGA HNSCC dataset we identified 8 potential mRNA targets (ESM1, KLF4, IL8, CCL20, IL24, CCNA1, TIMP4 and MMP1) from our validated 20 mRNA panel, which were aberrantly expressed in HNSCC and controlled by CELF1 in oral cancer cells." (PMID 26498364, 2015). "A recent publication identified IL24 as a potential biomarker for advanced disease in HNSCC; however, the exact mechanism of IL24 mRNA regulation in oral cancer cells is currently unknown." (PMID 26498364, 2015). "However, whether autophagy inhibition can enhance the acticancer effects of IL-24 in treating oral cancer is have not been investigated." (PMID 26361755, 2015).
osteosarcoma (7 papers, 2018 to 2025). A usually aggressive malignant bone-forming mesenchymal neoplasm, predominantly affecting adolescents and young adults. "IL-24 significantly inhibited the growth of tumors originating from osteosarcoma CSCs via downregulation of both Notch and Wnt/β-Catenin signaling." (PMID 40806452, 2025). "Patients with osteosarcoma who had high IL-24 levels had poorer EFS (p = 0.018), but slightly better OS (p = 0.040)." (PMID 41008853, 2025). "IL-24’s ability to block proliferation and decrease the stemness of osteosarcoma CSCs was initially tested in in vitro cultured cells and was subsequently translated into an in vivo pre-clinical model by using a nude mouse xenograft." (PMID 40806452, 2025). "LINC00473 interacts with the transcript factor C/EBPβ to facilitate its binding to the promoter of IL24, leading to recover the cisplatin-induced apoptosis in osteosarcoma." (PMID 30126852, 2018). "Consistently, it has been proved that adenoviral vector-mediated IL-24 expression suppresses the growth of MG-63 osteosarcoma cells through down-regulating Bcl-2 expression, and up-regulating Bax and Caspase-3 expressions." (PMID 29899165, 2018). "Similarly, elevated levels of individual cytokines and chemokines, including IL-24, CXCL5, and CXCL10, were associated with inferior event-free or overall survival in patients with osteosarcoma." (PMID 41008853, 2025).
asthma (6 papers, 2022 to 2025). "The role and underlying mechanism of other IL-24-positive cells in asthma airway inflammation, EMT and airway remodeling remain to be elucidated." (PMID 36100847, 2022). "Next, we interrogated whether alleviated AD-like inflammation caused by Il24 depletion could further the remission of atopic march, e.g., asthma." (PMID 38752989, 2025). "Furthermore, in vivo, IL-24 was highly expressed in mouse airway epithelium in a HDM-induced model of asthma, and this was associated with an upregulation of EMT markers." (PMID 37569787, 2023). "Consistently, the symptoms of asthma model, mimicking atopic march from epicutaneous sensitization, were relieved in Il24-deleted group." (PMID 38752989, 2025). "Collectively, the data suggest that IL-24 derived from keratinocytes drives the type 2 immune response and aggravates AD and asthma-like conditions." (PMID 38752989, 2025). "In a house dust mite (HDM)-induced mouse asthma model, IL-37 reduced airway eosinophil infiltration and remodelling by inhibiting IL-24-mediated EMT via modulation of STAT3 and ERK1/2 signalling." (PMID 41573715, 2025). "Although our results provided new insight into the mechanisms of IL-24 in asthma airway remodeling, there are also some limitations and issues worthy of further in-depth research." (PMID 36100847, 2022). "In vivo, we found that IL-24 was highly expressed in the mouse airway epithelium in an HDM-induced asthma model, which was accompanied by the upregulation of EMT markers." (PMID 36100847, 2022). "Next, lung function results showed that both si-IL-24 and IL-37 markedly attenuated airway resistance at Mch doses of 25 and 50 mg/ml compared with the asthma model group." (PMID 36100847, 2022). "Moreover, we found that IL-24 was significantly elevated in the lung tissues surrounding the airway epithelium in an HDM-induced asthma murine model." (PMID 36100847, 2022). "Overall, these results suggested that the inhibitory effect of IL-37 on the occurrence of EMT and remodeling in asthma may be related to its regulation of IL-24 levels by influencing the activation of the p-STAT3 and p-ERK1/2 signaling pathways." (PMID 36100847, 2022). "After intranasal si-IL-24 administration, the relative IL-24 expression was effectively inhibited in the HDM-sensitized murine asthma model." (PMID 36100847, 2022). "IL-24 shares two heterodimeric receptors (IL-20R1 and IL-20R2) with IL-19 and IL-20, and whether these receptors have similar or redundant biological effects on airway remodeling in airway epithelial cells or asthma models remains unclear and needs further examination." (PMID 36100847, 2022). "A murine asthma model was established by intranasal administration of house dust mite (HDM) extracts for 5 weeks, and the effects of IL-24 and IL-37 on EMT and airway remodeling were investigated by intranasal administration of si-IL-24 and rhIL-37." (PMID 36100847, 2022). "Whether the negative regulator IL-37 could exert a therapeutic effect on IL-24-mediated EMT in the bronchial epithelium, to regulate airway remodeling in asthma remains unclear." (PMID 36100847, 2022). "Hence, these results indicated that IL-24 could promote the migration ability and EMT process in BEAS-2B cells, which might contribute to the dysregulation of EMT in asthma." (PMID 36100847, 2022). "Overall, these findings indicated that IL-37 mitigated HDM-induced airway remodeling by inhibiting IL-24-mediated EMT via the ERK1/2 and STAT3 pathways, thereby providing experimental evidence for IL-24 as a novel therapeutic target and IL-37 as a promising agent for treating severe asthma." (PMID 36100847, 2022). "Thus, we hypothesized that IL-24 could facilitate the phenotypic switch from epithelial cells to mesenchymal cells and induce EMT, thereby contributing to the development of airway remodeling in asthma." (PMID 36100847, 2022).
asthma (continued). "However, little evidence has demonstrated the interaction between IL-24 and EMT-related airway remodeling in asthma, and the potential mechanism remains unclear." (PMID 36100847, 2022).
cervical cancer (6 papers, 2018 to 2026). A primary or metastatic malignant neoplasm involving the cervix. "combined cisplatin treatment with an IL‐24 expressing plasmid and noted a greater reduction in mean tumor weight in a cervical cancer xenograft model compared with the plasmid control‐treated group." (PMID 40338095, 2025). "The data obtained in this study underline the potential of a recombinant E7 DNA vaccine containing MDA7/IL-24 as a genetic adjuvant in abating and reversing cervical cancer progression in vivo." (PMID 35752792, 2022). "The results suggest a potential candidate adjuvant vaccine against HPV-related cervical cancer with high immunogenicity driven by using the anti-tumor MDA-7/IL-24 cytokine." (PMID 35752792, 2022). "A highly significant synergistic relationship was observed between the E7 DNA vaccine and the MDA-7/IL-24 cytokine against HPV-16+ cervical cancer models." (PMID 35752792, 2022). "The expression of IL24 by Ad- IL24 induces the apoptosis of cervical cancer cells by regulating the expression of proteins related to apoptosis, including PARK7." (PMID 32357493, 2020). "Furthermore, owing to the role of IL-10 cytokine in the progression of HPV-positive cervical cancer cells, we assessed if the IL-10 blockade improved the efficacy of the E7&IL-24 candidate vaccine against TC-1 tumor cells." (PMID 35752792, 2022). "Similar anti‐tumor benefits were reported in a study combining a therapeutic DNA vaccine with IL‐24 and IL‐10 blockade in models of HPV 16+ cervical cancer." (PMID 40338095, 2025). "Here we show that in HPV-transformed cervical cancer cells, MYPOP induces alterations in cell morphology, silences viral and cellular oncogenes including E6 and MYC, and stimulates the release of the cancer-killing cytokine interleukin-24." (PMID 42156885, 2026).
chronic lymphocytic leukemia (6 papers, 2010 to 2023). "Although high level IL-24 was linked to promoting chronic lymphocytic leukemia cell survival through activating p38 MAPK, several other preclinical studies demonstrated that the gene delivery of IL-24 through oncolytic adenoviruses elicited significant antileukemia effect in vitro and in vivo." (PMID 26554307, 2015). "Although the majority of studies have emphasized solid tumors, mda-7/IL-24 also induces ER stress and mitochondrial apoptosis pathway in human acute myeloid leukemia (AML) and chronic lymphocytic leukemia (CLL)." (PMID 26460950, 2015).
lung adenocarcinoma (6 papers, 2017 to 2025). A carcinoma that arises from the lung and is characterized by the presence of malignant glandular epithelial cells. "In vitro, infection of human lung adenocarcinoma cells (A549) with Influenza A virus induced a time-dependent upregulation of IL-24 mRNA and protein expression." (PMID 40943325, 2025). "Similarly, LINC00152 regulates expression of downstream gene IL24 via interacting with EZH2 in lung adenocarcinoma." (PMID 33292221, 2020).
allergic contact dermatitis (5 papers, 2019 to 2026). An inflammatory skin condition caused by an immune response to direct contact between the skin and an allergen. "To assess their role in ACD, we set up a mouse model of PPD-induced allergic contact dermatitis and we showed that, in contrast to Il22-deficient mice, Il22ra1-, Il20rb- and Il24-deficient mice are partially protected against development of PPD-induced contact hypersensitivity." (PMID 30755657, 2019). "Investigation into the role of IL‐24 in para‐phenylenediamine (PPD)‐induced allergic contact dermatitis (ACD) showed elevated IL‐24 levels in skin samples from patients allergic to PPD." (PMID 40338095, 2025).
Allergy (5 papers, 2019 to 2025). An allergy is an immune response or reaction to substances that are usually not harmful. "Preliminary studies indicate an association between IL‐24 and allergic diseases." (PMID 40338095, 2025). "In addition, we observed evidence of intercellular communication via genes implicated in type 2 immunity (CCL11, CCL13, CD5L, IL4, IL5, IL13, IL24) and allergy-linked inflammation (CCL19)." (PMID 35483355, 2022). "This includes gaining a deeper insight into its effects on various cell types within the wound niche and exploring how IL‐24 signalling intersects with other tissue repair mechanisms, particularly in the context of infection or allergy." (PMID 39835989, 2025). "IL‐24 plays a significant role in several allergic diseases." (PMID 39835989, 2025). "Further research focused on elucidating the biology and role of IL‐24 in CVD, eye diseases, infections, and allergies could help bridge the existing gaps and identify new treatment strategies." (PMID 40338095, 2025). "RASD2, IL24, CCL2 and CCL7 are immunologically relevant biomarkers in allergy." (PMID 33849432, 2021).
colitis (5 papers, 2011 to 2024). Inflammation of the colon. "Since other cytokines such as IL-20 and IL-24 also signal through IL-22Ra1, we used Il22−/− mice and observed that these mice were more susceptible to DSS-induced colitis as compared to wild-type controls." (PMID 38733584, 2024). "Compared with the control group, IL24 expression was increased in serum and colon samples from pediatric IBD patients and dextran sulfate sodium (DSS) induced colitis mouse models." (PMID 34925026, 2021). "To further study the role of IL-24 in intestinal pathophysiology, we investigated its expression in the colon of mice with DSS induced colitis." (PMID 34078403, 2021). "Those that were upregulated by 1 log fold or higher include IL-9, IL-13, IL-4, IL-17A, IL-5, IL-24, IFN-γ, IL-10, IL-11, and IL-27, many of which are known cytokines involved in the pathogenesis of colitis." (PMID 21365015, 2011).
head and neck squamous cell carcinoma (5 papers, 2019 to 2024). A squamous cell carcinoma that arises from any of the following anatomic sites: lip and oral cavity, nasal cavity, paranasal sinuses, pharynx, larynx, and salivary glands. "In our previous study, we used a Bifidobacterium breve as a delivery vector of IL-24 gene therapy (B. breve-IL24) for head and neck squamous cell carcinoma in vivo and discovered that B. breve-IL24 offers a novel, safe, and clinically acceptable therapeutic approach for tumor therapy." (PMID 35814447, 2022). "However, the expression level of the IL24 mRNA in head and neck squamous cell carcinoma (HNSCC) and its subgroups is rarely studied." (PMID 33014054, 2020).
leukemia (5 papers, 2013 to 2025). A malignant (clonal) hematologic disorder, involving hematopoietic stem cells and characterized by the presence of primitive or atypical myeloid or lymphoid cells in the bone marrow and the blood. "Inhibition of autophagy induced by overexpression of Mda-7/interleukin-24 strongly augments the anti-leukemia activity invitro and invivo." (PMID 37280571, 2023). "Conversely, expression of mda-7/IL-24 in leukemia cells induced autophagy, which was triggered by up-regulation of Beclin-1." (PMID 25590298, 2015). "IL-24 has also been reported to efficiently reduce the proliferation and induce apoptosis in myeloid leukemia cells and in leukemia stem like cells." (PMID 24377906, 2013). "As evident from the leukemia study, inhibiting autophagy will be beneficial for producing enhanced antitumor activity with IL-24." (PMID 24377906, 2013). "However, when the cells were treated with wortmanin, an autophagy inhibitor, IL-24-mediated autophagosomes were inhibited resulting in killing of the leukemia cells." (PMID 24377906, 2013). "Therefore, our results demonstrated that CD47-retargeted oncolytic adenoviruses armed with IL-24 could be valuable for the treatment of CD47+ leukemia." (PMID 26554307, 2015).
lymphoma (5 papers, 2012 to 2024). A malignant (clonal) proliferation of B- lymphocytes or T- lymphocytes which involves the lymph nodes, bone marrow and/or extranodal sites. "The therapeutic effect of LX/IL-24 modified tumor cells was also confirmed in murine lymphoma model (EL-4)." (PMID 31338417, 2019). "The protective effect of LX/IL-24-modified tumor cells was also examined in murine lymphoma model (EL-4)." (PMID 31338417, 2019).
oral squamous cell carcinoma (5 papers, 2015 to 2024). "For example, autophagy inhibitor chloroquine can enhance HDIL-2-mediated anti-tumor immunity by enhancing DC, T cells and NK cells, and 3-methyladenine (3-MA) can enhance IL-24-induced apoptosis against oral squamous cell carcinoma." (PMID 38262996, 2024). "However, whether IL-24 is effective to treat oral squamous cell carcinomas (OSCC) and if autophagy inhibition could improve the anticancer effect of IL-24 towards OSCC is has not been detected." (PMID 26361755, 2015). "In this study, the clinical implication of IL24 mRNA was evaluated in the common subgroups of HNSCC, including oral squamous cell carcinoma (OSCC), nasopharyngeal carcinoma (NPC), and laryngeal squamous cell carcinoma (LSCC) for analysis." (PMID 33014054, 2020). "Other research discovered that the autophagy inhibitor 3-MA significantly promotes IL-24-induced apoptosis in oral squamous cell carcinomas (OSCC), suggesting that combining 3-MA and IL-24 may be a potential method in immunotherapy." (PMID 36230955, 2022).